BRAF (B-Raf proto-oncogene, serine/threonine kinase)
Diseases named in the same sentence as BRAF in open-access papers (continued):
Sharing a sentence is not in itself a finding about the gene and the disease.
tumor (continued). "The tumor was KRAS, NRAS, and BRAF WT, and tumor mutational burden was 4 Mut/Mb." (PMID 41171165, 2025). "KRAS and BRAF hot-spot mutations were significantly different according to tumor sidedness." (PMID 39857025, 2025). "Furthermore, BRAF/MAPK pathway blockade is represented by inhibition of tumor-associated fibroblasts (TAFs) by modulation of interleukin-1 (IL-1), in particular by the transcription of IL-1α and IL-1β." (PMID 40872623, 2025). "Analyzing KRAS, NRAS, and BRAF hot-spot mutations at both the nucleotide and protein levels may offer insights into the mutational processes that influence tumor behavior, but functional studies are needed to validate these observations." (PMID 40075837, 2025). "Other tumor suppressor genes have been associated with outcomes of BRAF-targeted therapy." (PMID 40080754, 2025). "A positive result for MLH1 promoter methylation or BRAF mutation supports a sporadic tumor." (PMID 41463230, 2025). "Secondly, certain mutations even within the MAPK-ERK pathway, such as class-II BRAF mutations, may render the tumor resistant to BRAF- or MEK-inhibition." (PMID 39934281, 2025). "One tumour possessed a KIAA1549::BRAF fusion alongside VEGFR2, MSH6, and LRP1B variants." (PMID 39948623, 2025). "In this case, BRAF V600E mutation persisted in different stages of the tumor, suggesting that BRAF V600E gene mutation may play a key role in the progression of the tumor." (PMID 40535548, 2025). "Tumours displayed deficient MMR proteins with BRAF positivity, and germline testing confirmed LS." (PMID 40162154, 2025). "Patients aged > 80 (OR 0.36, 95% CI 0.32–0.40) had lower odds of having BRAF-mutated tumours." (PMID 40902091, 2025). "The tumor was KRAS, NRAS, and BRAF WT, and the tumor mutational burden was 6 Mut/Mb." (PMID 41171165, 2025). "KRAS, NRAS, and BRAF hot-spot mutations statistical analysis at both nucleotide and protein changes offers a more nuanced perspective and granular picture underlying mutational processes driving tumor formation in different colon regions." (PMID 39857025, 2025). "In parallel, a serrated neoplasia pathway—characterized by v-Raf murine sarcoma viral oncogene homolog B1 (BRAF) mutations, CpG island methylator phenotype (CIMP) and frequent MLH1 promoter hypermethylation—gives rise to a substantial subset of right-sided and microsatellite-unstable cancers." (PMID 41517288, 2025). "Overall, 40.5% of patients with available primary tumor tissue had a BRAF mutation in their tumor tissue (35.1% BRAFV600E, 2.7% BRAFV600R, BRAFV600K 2.7%), 18.9% of patients had a NRAS mutation (10.8% NRASQ61R, 8.1% NRASQ61K) and one patient (2.9%) had a KRAS mutation (KRASG12) in their tissue." (PMID 40652269, 2025). "The BRAF p.Val600Glu (V600E) mutation in the left-sided tumor is a potential target for molecular therapy and may have contributed to the lack of recurrence." (PMID 41473634, 2025). "Molecular analysis of the archival tumor tissue revealed the presence of the BRAF V600E mutation." (PMID 39935827, 2025). "Liquid biopsy evaluating circulating tumor DNA as a prognostic and predictive biomarker is informative and may help to guide treatment in patients with BRAF V600E mutated colorectal cancer." (PMID 39630848, 2025). "We hypothesized that higher BRAF V600E AF is positively correlated with increased tumor aggressiveness in MPTC, as a greater proportion of mutated DNA may drive oncogenic processes, leading to more aggressive clinical and pathological features." (PMID 40805249, 2025).
tumor (continued). "When applying these markers in the diagnostics of tumors of uncertain origin, it needs to be noted that loss of CDX2 and SATB2 expression was associated with higher tumor grade, proximal tumor location, BRAF mutation, and dMMR, which also corresponds with the findings of the previous studies." (PMID 39998677, 2025). "The BRAF V600E mutation in this tumor could be targeted with Encorafenib and Cetuximab as an approved combination for second‐line targeted therapy after chemotherapy." (PMID 39876058, 2025). "All tumours with Class I mutations exhibited concomitant BRAF or NRAS mutations." (PMID 40107205, 2025). "Clinically, BRAF V600E is associated with adverse pathological features and worse clinical outcomes, yet its isolated prognostic value is limited by confounding variables and heterogeneity in tumor behavior." (PMID 41368991, 2025). "Notably, after one year of follow-up, the tumor without the BRAF mutation (right side) recurred, whereas the BRAF-mutant left tumor remained in remission." (PMID 41473634, 2025). "We focus on several biomarkers commonly regarded as agnostic across tumor types, including BRAF V600E mutation, receptor tyrosine kinase (RTK) and PI3K fusions, the CpG island methylator phenotype (CIMP), high tumor mutational burden (TMB), and microsatellite instability (MSI)." (PMID 40868288, 2025). "Studies have shown that the BRAF V600E mutation can influence the tumour immune microenvironment by activating the MAPK pathway and may inhibit ferroptosis, suggesting its potential role in immune evasion and treatment resistance." (PMID 40299520, 2025). "Class 1 BRAF V600E-mutated is caused by c.1799T>A, suggesting the worst tumor biological behavior and poor prognosis, accounting for 90% of all BRAF-mutated in CRC according to a deeper classification system of BRAF-mutated derived from pre-clinical models functional studies." (PMID 40860811, 2025). "Additionally, the combination altered the tumor microenvironment by reducing immunosuppressive cell populations, including tumor-associated macrophages and regulatory T cells, which are typically increased following BRAF inhibitor therapy alone." (PMID 41333480, 2025). "Moreover, resistance to BRAF inhibitors has been associated with increased PD-L1 expression in tumor cells, resulting in PD-1 blockade, a strategy to restore or boost the effectiveness of BRAF inhibition." (PMID 40361336, 2025). "A lack of histologic review of this case precludes assessment of whether oncocytic features were present in any component of the tumor; however, the presence of a BRAF mutation would make a strong case for being a primary driver." (PMID 40277780, 2025). "Precise assessment of BRAF mutation status is essential not only for definitive tumor diagnosis and effective anti-BRAF targeted therapy (e.g., vemurafenib and dabrafenib) but also for providing crucial prognostic information regarding the nodule’s biological behavior and potential aggressiveness." (PMID 41409606, 2025). "At final histology, biological aggressive features, including multifocality, lymphovascular invasion (LVI), extracapsular invasion, tumor aggressive subtypes, and BRAF‐V600E mutation, were detected in 69 (34%), 93 (45.8%), 3 (1.5%), 30 (14.8%), and 7 (3.5%) patients, respectively." (PMID 39631795, 2025). "Targeted drugs and immunotherapy have been greatly applied in anti-tumor therapy: if there is a BRAF V600E mutation, BRAF V600 mutant kinase inhibitors can be used to inhibit the BRAF V600 mutant kinase, block the BRAF/MEK/ERK signaling pathway, and inhibit tumor cell proliferation and survival." (PMID 40502629, 2025). "By integrating the estimated purity of each tumor, the observed allele frequency of each mutation of interest, and the allele-specific copy numbers, we estimated a corrected allele frequency for the BRAF variant and the other Ras variant (details in Copy-number analysis and clonality estimates)." (PMID 39751654, 2025).
tumor (continued). "The absence of molecular and histopathological data, including microsatellite instability, KRAS/BRAF mutations, and tumor grade, limits the comprehensiveness of recurrence risk modeling and may contribute to residual confounding." (PMID 40936704, 2025). "Additionally, its expression correlated with tumour size, stage, lymph node metastases, tumour capsule invasion, and the BRAF mutation status were reported." (PMID 40141259, 2025). "One reason for the discordant results between tissue and cfDNA assays may be the determination of BRAF mutation status only in the predominant tumor nodule, considering the tendency for heterogeneous molecular profiles and the multifocality of PTC." (PMID 39336882, 2024). "Additionally, further validation of KRAS and BRAF V600E mutations in these tumours requires larger-scale sequencing data." (PMID 39484039, 2024). "A re-biopsy revealed the tumor had BRAF V600 and EGFR E746_A750del mutations." (PMID 39529955, 2024). "An indeterminate tumor is considered malignant if NGS results reveal BRAF or TERT mutations." (PMID 39235852, 2024). "Likewise, activated (V600E mutant) BRAF again in the context of INK4a loss, result in a high frequency of malignant gliomas, but also in poorly differentiated intrinsic tumours." (PMID 39324445, 2024). "coli+, and age at CRC diagnosis, tumour location, BRAF p.V600E mutation and CIMP-high." (PMID 38200234, 2024). "Only two studies have assessed the presence of BRAF mutations in feline tumours." (PMID 38787171, 2024). "These variations in the BRAF gene may cause constitutive protein activation, which results in uncontrolled cell proliferation and tumor formation." (PMID 38667446, 2024). "BRAF-mutated tumor cells may inhibit T cell activation and function by expressing immune checkpoint molecules (such as PD-L1), achieving escape from the immune system." (PMID 39529955, 2024). "It is noticeable that BRAF mutation analysis was conducted in four patients at tumor stage II." (PMID 39125519, 2024). "The ascites fluid was cytologically clear of tumor cells, but contained cell-free tumor DNA BRAF V600E-mutated (VAF = 47%) as measured by digital droplet PCR tests, whereas cell-free DNA circulating with peripheral blood contained the mutant allele at VAF = 1.6%." (PMID 39018206, 2024). "BRAF-mutated MSS tumours appear to have the worst prognosis." (PMID 39613865, 2024). "However, these inhibitors cause paradoxical activation of MAPK pathways by mediating RAF‐independent activation of MEK and ERK when used against tumours that are BRAF wild‐type or KIAA1549‐BRAF fused and can cause increased tumour progression and growth." (PMID 38299304, 2024). "The consensus highlights the importance of BRAF gene mutations in solid tumors and provides detailed information on mutation frequency, mutation types, detection methods, and drug-development progress across various tumor types." (PMID 39529955, 2024). "Furthermore, we observed an upregulation of FAK in specific tumor types with gene mutations or aberrant protein expression, such as BRAF/KRAS mutations, CDH1 deletions, EGFR or HER2 overexpression, and mediated drug resistance processes." (PMID 38410129, 2024). "However, BRAF mutation was still linked to increased infiltration of most analysed immune cells (with the exception of regulatory T cells) in the MSS tumours." (PMID 38040818, 2024). "Tumors harboring the BRAF V600E mutation may be treated with BRAF inhibitors; however, tumor response is often short lived due to multiple compensatory resistance mechanisms." (PMID 38275291, 2024).
tumor (continued). "Additionally, the study highlighted how those patients with BRAF-mutated tumours tended to exhibit increased FDG uptake, suggesting a potential for using SUV metrics as a prognostic marker." (PMID 39598062, 2024). "In summary, although our germline analyses did not reveal a potential explanation for tumor multiplicity in our LS individuals, we describe a non-random association of RNF43 hotspot variants to hypermethylator tumor phenotype that is distinct from the classical BRAF V600E-associated CIMP." (PMID 38725616, 2024). "If present, mutated BRAF is expressed in the cytoplasm of the tumour cell." (PMID 39591358, 2024). "Activating BRAF alterations may result in constitutive activation of this pathway, and are implicated in oncogenesis, leading to an increase in tumor growth and metastasis." (PMID 38791902, 2024). "BRAF mutation has been associated with MSI tumours, but is also found in MSS tumours." (PMID 38040818, 2024). "Similarly, thyroglobulin (TG) and BRAF V600E mutations were evaluated across subtypes to identify patterns correlating with tumor progression and prognosis." (PMID 39767732, 2024). "Furthermore, other investigations suggest a correlation between BRAF mutation and aggressive tumor features, such as increased mitotic rates and the presence of ulceration." (PMID 38396984, 2024). "Similarly, V-raf murine sarcoma viral oncogene homologue B1 (BRAF) and mitogen-activated protein kinase (MEK) inhibitors were recently approved with a tumour-agnostic indication for unresectable or metastatic solid tumours harbouring the BRAF V600E mutation." (PMID 38549846, 2024). "However, strong correlations between the KRAS/BRAF mutational status and tumor budding have been reported." (PMID 38248029, 2024). "Insights into tumor biology suggest that BRAF mutations contribute to more aggressive disease phenotypes and may influence therapeutic responses, particularly regarding anti-epidermal growth factor receptor antibody treatments in metastatic CRC." (PMID 39119381, 2024). "Also, whereas BRAF-mutated tumours displayed increased immune-cell infiltration compared to BRAF wild-type tumours, the opposite was seen for KRAS-mutated tumours, differences that were most prominent for cytotoxic T cells and Th1 cells." (PMID 38040818, 2024). "One case with BRAF wild type lost in vitro the POLE mutation demonstrated in the parental tumor." (PMID 39204387, 2024). "BRAF-mutated tumours have also been linked to a higher immune cell infiltration and expression of immunotherapeutic targets, but the relative contribution of mutated BRAF and MSI to the immune response remains uncertain." (PMID 38040818, 2024). "BRAF mutations may also impact the processes of autophagy and apoptosis in tumor cells, which are important for the activation of immune cells and the release of tumor antigens." (PMID 39529955, 2024). "BRAF mutations may affect the antigen-processing and -presentation mechanisms of tumor cells, reducing the expression of major histocompatibility complex molecules and weakening the ability of tumor cells to be recognized by the immune system." (PMID 39529955, 2024). "BRAF mutation has been linked to the immunogenic MSI tumours, but our findings partly suggest that BRAF and MSI may to some extent have individual effects on the immune response in CRC." (PMID 38040818, 2024). "By targeting P‐selectin, which is expressed on activated endothelial cells at the tumor site and tumor cells, the NPs showed improved accumulation in 3D spheroids and P‐selectin‐expressing tissues, such as BRAF‐mutated melanomas and BRCA‐mutated breast cancers." (PMID 39217459, 2024). "Here, we report the key characteristics of patients with atypical BRAF mutations identified from a large circulating tumor DNA database and a real-world clinical cohort, highlighting important differences, such as the presence of additional mutations and related survival outcomes." (PMID 38398128, 2024).
tumor (continued). "Our study identified FAK as a key regulator of BRAFV600E-induced ERK activation in mutant BRAF-induced serrated tumor formation/initiation and revealed that FAK loss allows BRAFV600E-induced ERK signaling to reach the permissive threshold “just-right” for cecal tumors to form." (PMID 36778401, 2024). "The tumour was resected and BRAF V600E mutation and exon 19 deletion were detected." (PMID 39139611, 2024). "However, BRAF mutations alone are typically insufficient to initiate tumor formation, as they are also commonly found in most benign nevi." (PMID 38891988, 2024). "Furthermore, in melanoma patients, serum IL8 levels were found to be linked with tumor size and stage, survival rates, and measurable treatment responses, including responses to BRAF inhibitors and immune-targeting monoclonal antibodies." (PMID 39766118, 2024). "Detection of BRAF mutations is clinically important in several tumor types." (PMID 38790156, 2024). "Currently, several anti-tumor drugs targeting BRAF mutations have been approved for the market." (PMID 39529955, 2024). "Similarly, data for 60 CRC patients regarding NRAS and BRAF mutation status were available showing that only 10% and 5% of these tumours presented mutations respectively." (PMID 38566765, 2024). "Moreover, regorafenib abrogates the angiogenic promotion of TAS102 in CRC cells and xenografted tumor tissues harboring with BRAF V600E mutation." (PMID 38953895, 2024). "BRAF-mutation is associated with MSI tumours, though it is also seen in MSS tumours." (PMID 39613865, 2024). "Similarly, 7% of tumors had BRAF V600E mutations, which are known to be targetable across several tumor types." (PMID 39191445, 2024). "Interestingly, the colon exhibited the highest BRAF mutation rate among the various primary tumour sites, which is consistent with previous research findings." (PMID 39484039, 2024). "Other candidates for targeted therapy are neoplasms with BRAF mutations." (PMID 39435876, 2024). "BRAF shows a statistically significant association with tumor grade." (PMID 39768914, 2024). "This study provides a comprehensive profile of BRAF variants in mCRC using a large genomic database of circulating tumor DNA (ctDNA) and analyzing clinical outcomes in a cohort of patients with atypical (non-V600) BRAF variants (aBRAF; class II, class III, unclassified)." (PMID 38398128, 2024). "In this manuscript, we performed a relatively large-scale study to determine the correlation between the percentage of tumor cellularity estimated by certified anatomic pathologists and VAFs of well-studied driver mutations detected in key oncogenes (i.e., BRAF, EGFR, KRAS, and NRAS)." (PMID 38397405, 2024). "Furthermore, combination therapy with Nivolumab and Ipilimumab (CTLA4 inhibitor), showed evident beneficial effects, especially for patients with BRAF-mutated tumours." (PMID 38040818, 2024). "CIMP is often seen in conjunction with MSI, particularly in tumours with BRAF mutations." (PMID 39456841, 2024). "Blood-based tumor mutation burden (bTMB) values were available in 258 patients with BRAF variants." (PMID 38398128, 2024). "Then, in counterfactual methods, the generative DL part can be used by a human experimentalist to answer questions such as “what would this particular tumor look like if it had a BRAF mutation?”, or “what would this precise tumor look like if the lymphocytes were removed?”." (PMID 38539231, 2024).